CCL20 (C-C motif chemokine ligand 20)
Diseases named in the same sentence as CCL20 in open-access papers (continued):
Sharing a sentence is not in itself a finding about the gene and the disease.
psoriasis (continued). "Serum biomarkers such as IL-6 and CCL20, elevated in preclinical models, correlate with subclinical enthesitis and may predict articular progression in psoriasis patients." (PMID 41583484, 2025). "Furthermore, the transcriptional signature from affected skin revealed upregulation of key human psoriasis genes, including Lcn2 and Defb4, cytokines Tnf, Il1b, and Il36a/g, and chemokine ligands Ccl2, Cxcl9, and Ccl20." (PMID 38528069, 2024). "Moreover, EGFR signaling has been shown to promote CCL20 production in a variety of cancers as well as in keratinocytes from psoriasis patients." (PMID 38472446, 2024). "And studies have shown that CXCL8 could recruit neutrophils and CCL20 chemotactically attracts IL-17A-producing immune cells, further creating an IL-17A-rich environment and accelerating the pathological progression of psoriasis." (PMID 38803495, 2024). "CCL20, in particular, plays a pivotal role in psoriasis by binding to its receptor CCR6." (PMID 38605947, 2024). "Nonetheless, Th17 cells are not the only subpopulation of immune cells expressing the CCR6 receptor, as CCL20 also shows a promigratory effect for Treg cells, and stimulation of CCL20 by oncostatin-M was found to be dispensable for psoriasis development in the animal model." (PMID 38672088, 2024). "Transcriptome analysis showed that CXCL13 and CCL20 were activated in both BC and psoriasis." (PMID 38605947, 2024). "CCL20 plays an important role in psoriasis by recruiting CCR6+Th17 cells into the lesional skin." (PMID 36035154, 2022). "Further studies showed that Daph could inhibit the NF-κB pathway, which was the key signaling pathway controlling the production of CCL20, an important inflammatory factor in terms of the pathogenesis of psoriasis." (PMID 35966027, 2022). "Psoriasis serum EVs promoted keratinocyte proliferation and the secretion of CCL20 and IL-8." (PMID 36035154, 2022). "Therefore, we believe that the therapeutic effect of Daph in psoriasis relies on the inhibition of keratinocyte proliferation and the inhibition of CCL20, which disrupts the inflammatory loop of psoriasis." (PMID 35966027, 2022). "Therefore, CCL20 is thought to be an important factor in mediating the pathogenesis of psoriasis in the IL-23/IL17 axis." (PMID 36620087, 2022). "In addition, secoligulene downregulated the expression of chemokines such as CXCL8 and CCL20 in the TNF-α/IL-17/IFN-γ induced HaCaT psoriasis model." (PMID 36015080, 2022). "This suggests the potential relevance of CCR6/CCL20 as a therapeutic target for psoriasis." (PMID 33732249, 2021). "Previously, CCL20 was known for its antimicrobial activity and involvement in autoimmune diseases such as inflammatory bowel disease, rheumatoid arthritis and psoriasis." (PMID 34569432, 2021). "Among the chemokines, CCL20 is a major contributor to immune cell infiltration in psoriasis." (PMID 34054833, 2021). "CCL20 produced by keratinocytes recruits Th17 cells contributing to inflammation in psoriasis but may contribute to an immunosuppressive environment through recruitment of immunomodulatory immune cells in the tumor microenvironment." (PMID 33916486, 2021). "Targeting the CCL20/CCR6 axis may be a potential therapeutic strategy for the treatment of psoriasis." (PMID 32070069, 2020). "The lesional epidermal keratinocytes express abundant CCL20 in patients with psoriasis." (PMID 31936670, 2020). "In addition to this axis representing the core of psoriasis pathogenesis, upstream cytokines (IFN-α, IFNγ, and TNFα), synergizing cytokines (IL-22 and TNFα), and downstream mediators (IL-8, IL1F9, and CCL20) complete the pathogenic puzzle." (PMID 29316717, 2018). "The expression of Th1 and Th17 recruiting chemokines CXCL1, CXCL8 and CCL20 is upregulated in psoriasis skin but the precise contribution of DCs to chemokine secretion in psoriasis is unknown." (PMID 25301671, 2015).
psoriasis (continued). "The critical role of CCR6 in psoriasiform inflammation was well documented by the observation of expression of CCR6 and CCL20 in psoriatic lesions and by the finding that both IL-17A- and IL-22-producing cells isolated from lesional skin of patients with psoriasis displayed CCR6." (PMID 21311769, 2011). "Therefore, CCL20 has also been studied as a possible therapeutic target for psoriasis." (PMID 35966027, 2022). "A comparative study revealed differential expression of chemokines in AD (CCL17/18/20) and psoriasis (CXCL1, IL-8, and CCL20), indicating that disease-specific microenvironments might be involved in Th differentiation While psoriasis is Th17/Th22-skewing, AD tends to be Th2/Th22 polarized." (PMID 35911703, 2022). "It has been suggested that CCR6/CCL20 could be a potential therapeutic target for psoriasis." (PMID 24223818, 2013). "Proteins related to the central disease‐driving pathways of psoriasis, namely the TH1 (CCL3, CCL4, CXCL9, CXCL10, CXCL11, TNFα) and TH17 pathway (CXCL1, CCL20, IL‐17A, IL‐12B) were found elevated in lesional skin across both studies." (PMID 40970551, 2025). "MSC exosomes also suppressed DC maturation and activation and inhibited the release of pro-inflammatory cytokines (TNF-α, IFN-γ, IL-1β), chemokines (CCL20 and CXCL8), and psoriasis-specific cytokines (IL-23)." (PMID 41007656, 2025). "CCL20, IL-6, IL-20, IL-17C, and PI3 were previously found to be elevated in patients with psoriasis." (PMID 39224116, 2024). "A number of serum analytes identified by Olink analysis, including PI3, IL-17C, CCL20, IL-20, IL-6, CXCL9, and CXCL10, have been previously identified as being elevated in serum samples of patients with psoriasis." (PMID 39224116, 2024). "TNF‐α, IL‐1β, IL‐23, IL‐17, IL‐22, Cox2, and iNOS are all inflammatory cytokines involved in the pathogenesis of psoriasis, and CXCL1, CXCL8, and CCL20 are antimicrobial peptides and chemokines produced by keratinocytes." (PMID 38967379, 2024). "Therefore, the CCR6/CCL20 axis may be a promising target for treating psoriasis." (PMID 37092451, 2023). "Thus, the CCL20/CCR6 axis could be a novel promising target for treating psoriasis." (PMID 37049538, 2023). "We examined the expression of cytokines previously reported to be involved in psoriasis, and found that IL17A, IL17F, IL26, CCL20, CXCL13, IL22, and IL23R were specifically expressed by Tc17 cells." (PMID 37308489, 2023). "CCL20 is also involved in controlling the immune response, and has been found to be overexpressed in inflammatory bowel disease (IBD), psoriasis and rheumatoid arthritis, leading to the occurrence of autoimmune diseases (AIDs)." (PMID 36447119, 2023). "A further investigation of the effect of compounds 1 on psoriasis showed a dramatic decrease in the levels of chemokines, CCL8 and CCL20 in the TNF-α/IL-17/IFN-γ-induced HaCaT psoriasis model." (PMID 36015080, 2022). "In the current study, the levels of IL-6, IP-10/CXCL10, MIP-3α/CCL20, and ICAM-1 were upregulated in M5-stimulated HaCaT cells (in vitro model of psoriasis)." (PMID 35209199, 2022). "In support of the Role of IL-17A in the Psoriasis Pathway, CXCL1, CXCL3, CXCL6, S100A8, S100A9, and CCL20 in the shared signature were all upregulated in both psoriatic skin and colon lesional tissues." (PMID 36396672, 2022). "Glycyrrhizin is a therapeutic substance that improves psoriasis by down-regulating IL-17A and INF-γ, and further inhibits the expression of IL-6, TNF-α, and CCL20 induced by IL-17A." (PMID 34044769, 2021). "This demonstrates that CCL20, together with its receptor, CCR6, are potential targets for the treatment of psoriasis." (PMID 33732249, 2021). "After injection of LCN2 into imiquimod (IMQ)-induced psoriasis-like skin, the mRNA expression levels of IL17A, CXCL1, CCL20, S100A7, and other cytokines and chemokines increased, which supports our analysis results." (PMID 33613635, 2021).
psoriasis (continued). "A first-in-human study using a humanized anti–CCL20 antibody, GSK3050002, has already been reported for the treatment of psoriasis." (PMID 31936670, 2020). "Our study underscores the potential role of new therapies such as anti-CCL20 antibody and EGFR/ERK inhibitors in the management of psoriasis." (PMID 31936670, 2020). "Cytokine and chemokine expression levels in the mouse skins were also determined because expressions of IL-6, IL-17, IL-22, CCL20 and CXCL1 were involved in the pathogenesis of psoriasis." (PMID 29138509, 2017). "Taken together, these data suggest that ERDR1 regulates Th17 cell migration towards psoriatic lesional skin through the inhibition of the CCL20/CCR6 axis, resulting in the attenuation of psoriasis-like skin inflammation." (PMID 26901187, 2016). "In conclusion, we demonstrate that the cytokines-mediated overexpression of IFI16 contributes to the pathogenesis of psoriasis by activating the TBK1-NF-κB signaling pathway and then inducing the production of CXCL10 and CCL20 in keratinocytes." (PMID 27137868, 2016). "We demonstrated that psoriasis-related transcripts, such as IFN-γ, TNF-α, IL-17A, CCL20, IL-23, IL-6, IL-1α and IL-22, were significantly enhanced in mouse ears treated with PL and rMCP-1 than those with 1×PBS control." (PMID 21311769, 2011). "CCL20 (also known as MIP-3α) acts as a chemotactic factor that, through binding with its receptor CCR6, is crucial for transporting IL-17A-producing T cells from the bloodstream to the skin during the progression of psoriasis." (PMID 39861704, 2025). "The unique engagement between CCL20 and CCR6 is considered essential in developing psoriasis." (PMID 40343299, 2025). "Notably, the CCR6 on the surface of FV@CX5461 facilitated targeted delivery to CCL20-rich inflamed skin areas, thereby restoring immune balance and mitigating IMQ-induced psoriasis symptoms." (PMID 41226338, 2025). "Bimekizumab treatment completely reversed the levels of cytokines/chemokines, anti‐microbial peptides, or proliferation‐related molecules, such as CXCL8, CCL20, IL‐17A, IL‐17F, IL‐17C, keratin 16, IL‐36γ, DEFB4, or S100A7, in psoriasis lesional skin to the levels of non‐lesional skin." (PMID 38482898, 2024). "CCL20, also known as MIP-3α or LARC, is an important chemokine in psoriasis." (PMID 38008779, 2023). "In several animal models of psoriasis, the use of anti‐TNF‐α antibody infliximab, anti‐CCR6 antibody, and the anti‐CCL20 antibody, respectively, significantly reduced regional infiltration of CCR6+CD4+ T cells and attenuated the inflammatory response in affected skin lesions." (PMID 35702353, 2022). "Chemokines such as CCL20 and MCP-3/CCL7 are stimulated by Th17 cell cytokines, e.g., IL-17A, which may contribute to a positive IL-17 response feedback loop in psoriasis." (PMID 35008981, 2022). "In mouse models of psoriasis CD200R1 was shown to limit psoriasis‐like inflammation by enhancing acanthosis, CCL20 production and neutrophil recruitment, but surprisingly, macrophage function and IL‐17 production were not affected, and neutrophil reactive oxygen species production was reduced." (PMID 35759230, 2022). "To understand the molecular mechanism of N4BP1 in the regulation of neutrophil infiltration, we examined the mRNA level of several key genes involved in inflammation including TNFa, IL-23, IL-17, CXCL1, CCL20, S100A8, and S100A9 in psoriasis skin from N4BP1 KO and WT mice." (PMID 33990547, 2021). "In addition, IL-24 overexpression in psoriasis prompts the expression of pro-inflammatory chemokines CXCL1, CXCL8, and CCL20." (PMID 34638757, 2021). "Deletion of CCR6 or the dominant-negative form of CCL20 ameliorates skin symptoms in psoriasis model mice, thus suggesting the indispensable role of the CCL20/CCR6 axis in the pathogenesis of psoriasis." (PMID 34361983, 2021).
psoriasis (continued). "Since CCL20 is a ligand for CCR6, which is a signature molecule of IL-17A-producing T cells, the activated keratinocytes in the disease-naïve sites of psoriasis are to recruit IL-17A-producing T cells to the disease-naïve sites, leading to the accumulation of IL-17A-producing TRM." (PMID 34501272, 2021). "CCN1 produced by fibroblasts of the imiquimod/IL-23-induced psoriasis mice aggravates epidermal hyperplasia and inflammation through JNK-mediated upregulation of CCL20 and IL-8 and subsequent recruitment of CCR6+ dendritic cells and T-cells into inflamed skin tissue." (PMID 32252279, 2020). "The JAK/STAT signaling and spleen tyrosine kinase (SYK) pathways are implicated in numerous autoimmune and inflammatory diseases (e.g. AD, psoriasis, alopecia areata), modulating a range of immune responses, including the Th2 (IL-4, IL-13, CCL18), Th1 (IFNγ), and Th17/Th22 (CCL20, S100As) pathways." (PMID 33329590, 2020). "Dysregulated Th17 cells and IL-17 synthesis in the skin, synovial space and endothelium promote synthesis of pro-inflammatory cytokines namely IL-1β, TNF and IL-6 and neutrophil chemoattractants such as IL-8, CCL20 and CCL2 as observed in psoriasis and psoriatic arthritis." (PMID 33737877, 2020). "Scratch injury upregulates the gene expression of CCL20, CXCL8, and IL36G, which may be related to the scratch-induced Koebner phenomenon frequently observed in patients with psoriasis." (PMID 32070069, 2020). "Based on the IPA analysis BmA pre-exposure before LPS E. coli re-stimulation affected several pathways like granulocyte and agranulocyte adhesion and diapedesis (PPBP/CXCL7, PECAM1, CCL20, CXCL5, CXCL6, MMP9), IL-17 in psoriasis, arthritis and signaling in airway cells (CCL20, CXCL5, CXCL6)." (PMID 30796272, 2019). "Besides upstream regulation of IL-23, TNF-α can act synergistically with IL-17A on epidermal keratinocytes, resulting in overexpression of various psoriasis-related proinflammatory gene including S100A7, IL-8, DEFB4, CCL20 and CXCL1." (PMID 29232931, 2017). "Importantly, in a mouse model of psoriasis, p204 knockdown improved epidermal hyperplasia, alleviated skin inflammation and reduced the expression levels of CXCL10 and CCL20." (PMID 27137868, 2016). "In addition, downregulation of CCL20 and CCR6 by rERDR1 administration was also detected, implying that ERDR1 alleviates the psoriasis-like skin inflammation through the regulation of Th17 cell distribution in lesional skin." (PMID 26901187, 2016). "Similar to the CCL19/CCL21/CCR7 axis, the CCL20/CCR6 axis serves an essential role in the recruitment of inflammatory cells in the immune response and may contribute to a variety of autoimmune diseases, such as MS, IBD, psoriasis, and RA." (PMID 35702353, 2022). "The loss of IL-17A/PASI correlation in the presence of atherosclerotic CVD, together with the decreased correlations of PI3, IL-17C, CCL20 and TGF-α with PASI in these patients, clearly merits further investigation and may contribute to further understanding of the links between psoriasis and CVD." (PMID 35008981, 2022). "Furthermore, IL-1β stimulation of NHEKs was found to induce upregulation of the mRNA and protein levels of pro-inflammatory cytokines, chemokines and antibiotic peptides including IL-36γ, CXCL1, CXCL2, CCL20, S100A7, S100A8 and S100A9, which are closely related to the pathogenesis of psoriasis." (PMID 32194991, 2020). "NLP keratinocytes produce increased amounts of CCL20 upon stimulation with Candida albicans or mannan suggesting the role of KC, weakly stimulated by resident fungi, in accumulation of IL-17 and IL-22 producing CCR6-positive resident T cells in NLP skin of psoriasis patients." (PMID 32276410, 2020). "IL-17A acts in synergism with other key-cytokines in psoriasis such as TNF-α and IL-22, stimulating the expression AMPs (LL37, β-defensins, LCN2, S110A family proteins), inflammatory cytokines (IL-1 family members and IL-6), and chemokines (CXL1, -3, -5, -8, and CCL20)." (PMID 29316717, 2018).
psoriasis (continued). "For example, chemokines like MIG/CXCL9, IL-10/CXCL10, IL-8/CXCL8, MCP-1/CCL2 and MIP-3α/CCL20 released from epidermal keratinocytes function as potent chemoattractants for monocytes, neutrophils, Langerhans cells, DCs and T cells, which are key cells in psoriasis." (PMID 29232931, 2017). "Importantly, CXCL10 and CCL20 expressions were decreased in the psoriasis-like lesions in the absence of p204, which was accompanied by a decrease in the phospho-p65 level and inhibition of p65 nuclear translocation in epidermal cells." (PMID 27137868, 2016). "Based on increasing evidence for the importance of the CCR6+ Th17 cell population in psoriasis, we suggest that a decreased distribution of CCR6+ Th17 cells in psoriatic lesional skin via the regulation of CCL20 may be a critical mechanism for ERDR1-regulated psoriasis." (PMID 26901187, 2016). "However, a significant number of genes which may be induced by IL-23 or IL-22 such as GRO-1 (CXCL1), S100A7, S100A8, STAT3, IL-6, SCYA20 (CCL20), SCYA22 (macrophage-derived chemokine/CCL22), and β-defensin 2 have been identified in psoriasis microarray studies." (PMID 19884985, 2009). "While the marker cytokines of psoriasis were virtually non-detectable in non-lesional skin, chemokines CXCL10 and CCL20, the respective chemoattractants for Th1 and Th17 cells, were significantly increased." (PMID 28790368, 2017). "We confirmed that endogenous TWEAK was required for maximal expression of CCL2, CCL5 and CCL7, and furthermore, we found defective production of CCL17 and CCL20 in mice lacking TWEAK in the AD model and the psoriasis model, respectively." (PMID 28530223, 2017). "One can observe that the top psoriasis genes, including IFNg genes OASL, MX1; IL17-regulated CCL20 and IL19 are not different in the PPPP/PPP as compared with normal acral skin." (PMID 27152848, 2016).